JUN (Jun proto-oncogene, AP-1 transcription factor subunit)
Diseases named in the same sentence as JUN in open-access papers (continued):
Sharing a sentence is not in itself a finding about the gene and the disease.
oral cancer (11 papers, 2016 to 2024). "Analysis of clinical samples of oral cancer found a strong correlation of these genes with short survival, especially JUN expression associated with metastasis." (PMID 30459815, 2018). "The results suggest that c-JUN is strongly correlated with oral cancer metastasis." (PMID 30459815, 2018). "Silencing expression of CCND1, JUN and SPP1 in the human oral cancer cell line OECM-1 confirmed that those genes play essential roles in oral cancer cell invasion." (PMID 30459815, 2018). "To confirm the function of CCND1, JUN and SPP1 in oral cancer cell invasion, we knocked down expression of CCND1, JUN and SPP1 through siRNA in the human oral cancer cell line OECM-1 and examined the alteration of cell invasion ability." (PMID 30459815, 2018). "We focused on those 28 common DEGs that show consistent changes in both datasets and defined a “metastasis signature”: CCND1, JUN and SPP1 for oral cancer lymph node metastasis." (PMID 30459815, 2018). "We further tried to explore the correlation of expression of CCND1, JUN and SPP1 with oral cancer metastasis through statistically analyzing the clinic data in the literature." (PMID 30459815, 2018). "Our study identified a novel “focal adhesion”-related gene signature (CCND1, JUN and SPP1) that might be applicable for diagnosis of oral cancer metastasis to lymph nodes." (PMID 30459815, 2018). "The result further supports the hypothesis that the focal adhesion-related gene signature (CCND1, JUN and SPP1) is important for oral cancer invasion." (PMID 30459815, 2018). "Our study identified a novel focal adhesion-related gene signature (CCND1, JUN and SPP1) that might be important for oral cancer metastasis to lymph nodes." (PMID 30459815, 2018). "Our study identified a unique gene signature – CCND1, JUN and SPP1 – which may be involved in oral cancer lymph node metastasis." (PMID 30459815, 2018). "In sum, this study identifies a unique gene signature – CCND1, JUN and SPP1 – which could be a new early biomarker for diagnosing oral cancer lymph node invasion and metastasis." (PMID 30459815, 2018). "Through bioinformatics analysis of the gene expression profile of oral cancer metastatic and non-metastatic lymph nodes and primary tumors, we identified a new oral cancer metastatic gene signature: CCND1, JUN and SPP1." (PMID 30459815, 2018).
osteoporosis (11 papers, 2018 to 2025). A condition of reduced bone mass, with decreased cortical thickness and a decrease in the number and size of the trabeculae of cancellous bone (but normal chemical composition), resulting in increased fracture incidence. "Our study results revealed that a binding site SNP of the TF, JUN, rs130347, was significantly associated with osteoporosis." (PMID 35748775, 2022). "The transcription factor JUN is considered a new therapeutic target for osteoporosis-related fractures." (PMID 40299567, 2025). "Additionally, PPARG, PTGS2, IL6, STAT3, and JUN have been reported to play important roles in the development of osteoporosis." (PMID 40299567, 2025). "Several hub genes, including JUN and ACSL5, were found and may represent potential biomarkers or clinical targets for osteoporosis." (PMID 33329745, 2020).
renal cell carcinoma (11 papers, 2015 to 2025). "LncRNA SCAMP1 has been reported to regulate ZEB1/JUN axis in renal cell carcinoma." (PMID 35992869, 2022). "Moreover, miR-429 targets both ZEB1 and JUN in renal cell carcinoma cells." (PMID 35992869, 2022). "Therefore, lncRNA SCAMP1 enhanced progression of renal cell carcinoma via regulation of autophagy and miR-429/ZEB1/JUN axis under oxidative stress." (PMID 35992869, 2022).
sarcoma (11 papers, 2011 to 2025). A usually aggressive malignant neoplasm of the soft tissue or bone. "JUN is a protein-coding gene and has no introns; it is located in 1p32-p31: a chromosomal region involved in human malignant translocations and deletions JUN-related diseases, include sarcomas and whooping cough." (PMID 32038705, 2019). "Amplification of the JUN oncogene has been reported in human liposarcomas, in sound accordance with herein discovered frequent Jun amplification in MD mixed sarcomas." (PMID 21533183, 2011). "Several of the FET-sarcoma-specific and shared transcription factors formed a protein interaction network, with MLS-specific JUN, RUNX1, FOSL2, and CREB5 as center nodes." (PMID 40988026, 2025). "Analysis using the U133Plus gene expressions expands this result by including JUN (JUN oncogene), MAPK8 (mitogen activated protein kinase 8), SRC (v-SRC sarcoma) and FYN (FYN oncogene related to SRC) as protein kinases within dasatinib’s discriminating genes." (PMID 23056181, 2012).
acute myeloid leukemia (10 papers, 2009 to 2025). Acute myeloid leukemia (AML) is a group of neoplasms arising from precursor cells committed to the myeloid cell-line differentiation. "Moreover, in acute myeloid leukemia JUN was recently found to be involved in the transcription of the UPR transcription factors XBP1 and ATF4." (PMID 29423023, 2018).
epilepsy (10 papers, 2017 to 2025). A brain disorder characterized by episodes of abnormally increased neuronal discharge resulting in transient episodes of sensory or motor neurological dysfunction, or psychic dysfunction. "We have identified six feature genes (IL6, PTGS2, HMOX1, NFE2L2, TLR4, and JUN) strongly associated with ferroptosis in epilepsy, suggesting their potential as biomarkers for the diagnosis of temporal lobe epilepsy." (PMID 37946105, 2023). "In this research, we identified six characteristic genes associated with ferroptosis in epilepsy: NFE2L2, PTGS2, IL6, JUN, HMOX1, and TLR4." (PMID 37946105, 2023). "Based on the present results, ferroptosis-related hub genes NFE2L2, PTGS2, IL6, JUN, HMOX1, and TLR4 have good diagnostic value for epilepsy and may be potential early biological diagnostic targets." (PMID 37946105, 2023). "Besides, the c-JUN-medicated signaling pathway was an important BP involved in the pathogenesis of hippocampal neuronal damage in kainite-induced epilepsy." (PMID 36389252, 2022).
Hypertension (10 papers, 2012 to 2025). The presence of chronic increased pressure in the systemic arterial system. "Other common target genes were vascular endothelial growth factor A (VEGFA), forkhead box 01 (FOX01), and jun proto-oncogene (JUN) for miR-532-5p and miR-133a-3p, which were associated with cancer and mechanisms related to inflammation, hypertensive disease, and myocardial ischemia (VEGFA and JUN)." (PMID 34440025, 2021). "In ocular hypertensive DBA/2J mice, JUN was expressed prior to RGC death after ocular hypertensive injury." (PMID 28726785, 2017). "Furthermore, we first investigated the expression patterns of the hypertension drug‐related genes in COVID‐19 patients by data set mining and modeling, suggesting the molecules being potentially involved in both hypertension and COVID‐19 pathology, such as JUN, LST1, and SLC18A2." (PMID 35656698, 2022). "The effect of estrogen, androgen and cytokines are reflected on clusters of estrogen and androgen receptors, STAT5, JUN, MYC and other TFs binding at ACE2 regulatory regions, where hypertension QTLs and the great majority of ACE2 eQTLs are also mapped to." (PMID 32558150, 2020). "JUN (a PCOSrp) plays a role in mitophagy, and it was also identified as a shared protein between PCOS and hypertension." (PMID 31216618, 2019).
ischemic stroke (10 papers, 2017 to 2025). A stroke disorder caused by obstruction of blood flow to the brain, due to thrombotic (local blood clot formation) or embolic (due to a blood clot or other material traveling from another site) event. "It was reported that HSC70 or eEF1A1 knockdown increases phosphorylated JNK, phosphorylation of c‐JUN, cleaved caspase‐9, and cleaved caspase‐3 expression in the background of ischemic stroke, which could be rescued by SP600125." (PMID 39764606, 2025). "Using this approach, we identified a distinct gene signature—termed GSERK—including GADD45A, DUSP1, EREG, IL1B, JUN, and GADD45B as central regulatory nodes within ischemic stroke-related co-expression networks." (PMID 40636523, 2025). "After filtering out the common targets of FIB and Ischemic Strokes, 31 targets were screened for constructing the PPI network, and the top four core targets (CASP3, PTGS2, JUN, and HSP90AA1) were finally determined." (PMID 36467049, 2022). "CASP3, PTGS2, JUN, SLC6A4, and HSP90AA1 rank the top five in terms of degree value, indicating that these targets may be the key targets for FIB to treat ischemic strokes." (PMID 36467049, 2022).
peripheral nerve injury (9 papers, 2012 to 2025). Injury to a peripheral nerve. "Inhibition of PTEN promotes axonal regrowth, and downregulation of c-JUN facilitates remyelination in peripheral nerve injury." (PMID 40950414, 2025). "Activation of ERK and c-JUN plays a key role in peripheral nerve injury." (PMID 34769029, 2021). "It has been suggested that transcription factors such as ATF3, JUN and SOX11 may be important in the regulation changes in ion channel function and their accessory subunits after peripheral nerve injury." (PMID 31620455, 2019).
endometriosis (8 papers, 2013 to 2025). The growth of functional endometrial tissue in anatomic sites outside the uterine body. "In the high JUP group, we identified several downregulated genes in the PBMCs from endometriosis patients, including HBB, HBA1, HBA2, RGPD2, CH25H, LTB, IFIT2 and JUN." (PMID 39684780, 2024). "miR-200b-3p was associated with the transcription factors DNMT1, EZH2, HNF1B, JUN, MYB, ZEB1, and ZEB2 during the pathogenesis of endometriosis." (PMID 32802844, 2020). "Then, DNMT1, EZH2, HNF1B, JUN, MYB, ZEB1, and ZEB2 were found as TFs related to endometriosis by interacting with target genes of miR-200b-3p." (PMID 32802844, 2020). "The top 5 genes were the following: EGFR, EZH2, VEGFA, JUN, and FN1 with a degree >15; thus, they might be regulated by miR-200b-3p and play important roles in the progression of endometriosis." (PMID 32802844, 2020). "Comparison between participants without endometriosis (n = 5) and participants with endometriosis (n = 4) with high serum JUP values (>220 ng/mL) identified nine DEGs (HBB, HBA1, HBA2, and RGPD2 in CD14+ monocytes; CH25H, HBB, LTB, and KLRC1 in γδt; IFIT2 in NK-CD56bright and JUN in Treg)." (PMID 39684780, 2024).
head and neck squamous cell carcinoma (8 papers, 2021 to 2024). A squamous cell carcinoma that arises from any of the following anatomic sites: lip and oral cavity, nasal cavity, paranasal sinuses, pharynx, larynx, and salivary glands. "In NSCLC and head and neck squamous cell carcinoma (HNSCC) cells, JUN overexpression coincides with acquired resistance to cetuximab and is accompanied by increased expression of AXL." (PMID 35572601, 2022).
hepatitis B (8 papers, 2019 to 2025). "In addition, a dysregulated level of JUN is associated with several liver diseases including hepatitis B virus infection, metabolic dysfunction-associated steatotic liver disease (MASLD) and tumorigenesis." (PMID 39878507, 2025). "The 2 components of Radix Paeoniae Alba play an auxiliary role in treating hepatitis by binding targets AKT1 and JUN and activating Hepatitis B, Hepatitis C, and other pathways." (PMID 38050220, 2023). "Our result showed that JUN was involved in Hepatitis B, NOD-like receptor signaling pathway, AGE-RAGE signaling pathway in diabetic complications, Pathways in cancer, IL-17 signaling pathway, TNF signaling pathway." (PMID 31138194, 2019).
injury (8 papers, 2011 to 2025). Damage inflicted on the body as the direct or indirect result of an external force, with or without disruption of structural continuity. "Beyond direct regulation of Cbln2, SOX11 may influence broader transcriptional programs through interactions with downstream factors such as ATF3 and c-JUN, both of which are well-established contributors to neuropathic pain following nerve injury." (PMID 41162740, 2025).
liposarcoma (8 papers, 2010 to 2025). A usually painless malignant tumor that arises from adipose tissue. "CDKN2A/B), amplifications (e.g. JUN in liposarcoma), fusion partners (e.g. PAX3/7::FOXO1 in rhabdomyosarcoma), breakpoint positions in fusions (e.g. NAB2::STAT6 in SFT) and the extent of segmental (i.e. sub-chromosomal arm) copy number changes (e.g. synovial sarcoma)." (PMID 38997407, 2024). "Chromosomal imbalances additionally to the 12q13-q15 amplicon, including amplifications in 1p32 (including JUN), 1q21-q24, and/or 6q23 (including the ASK1 or MAP3K5 gene), have been reported to be more frequent in dedifferentiated liposarcoma than in well-differentiated liposarcoma." (PMID 25713799, 2015).
schizophrenia (8 papers, 2007 to 2024). A major psychotic disorder characterized by abnormalities in the perception or expression of reality. "Notably, MEF2C is also implicated in schizophrenia through GWAS46 and encodes a transcriptional regulator of activity-dependent immediate early genes such as JUN and FOS47." (PMID 35760976, 2022). "Finally, JUN is up-regulated in post-mortem brains of schizophrenia patients whereas the neuro-specific expression of TAF1 has been related to another neurological disorder: X-linked dystonia-parkinsonism." (PMID 17849003, 2007).
skin cancer (8 papers, 2015 to 2025). "In addition, we demonstrate that the reduced proliferative capacity of HPV + cells observed upon JNK1/2 inhibition is at least partially due to a defect in EGFR signalling, which has previously been shown in skin tumours in which the JUN gene has been deleted." (PMID 33303976, 2021).
thyroid cancer (8 papers, 2017 to 2025). "Additionally, survival analysis using TCGA prognostic data revealed that low expression of JUN was significantly associated with disease-free survival (DFS) in thyroid cancer patients (P = 0.0058)." (PMID 40092686, 2025). "Moreover, FOS and JUN expression alterations in FTC, along with SFN upregulation in PTC, further highlight these genes as promising diagnostic candidates for specific thyroid cancer subtypes." (PMID 40722651, 2025). "Components of the AP-1 transcription factor, including JUN, JUNB, FOS, FOSB, were enriched in association with TTP as a conserved co-regulated group of genes and were significantly downregulated in breast, liver, lung, kidney, and thyroid carcinomas." (PMID 32545247, 2020).
acute kidney injury (7 papers, 2010 to 2025). Sudden and sustained deterioration of the kidney function characterized by decreased glomerular filtration rate, increased serum creatinine or oliguria. "However, for samples pathologically characterized with acute kidney injury labeled as injured kidney, JUN expression is prominent in the proximal tubule cluster." (PMID 35701599, 2022).
autoimmune disease (7 papers, 2020 to 2025). A disorder resulting from loss of function or tissue destruction of an organ or multiple organs, arising from humoral or cellular immune responses of the individual to their own tissue constituents. "JUN-related pathway is one of the key signaling pathways in autoimmune diseases and is closely related to physiological processes such as cell proliferation, cell differentiation, cell survival, cell death and immune response." (PMID 38637111, 2024). "A study found that the ERK-JNK-P38 signaling pathways in autoimmune disease are activated, leading to high levels of downstream JUN and Fos protein." (PMID 32908565, 2020). "c-JUN was a pathway closely related to a variety of autoimmune diseases." (PMID 35265149, 2022). "JUN and FOS are subunits of the transcription factor AP-1 which regulates cytokines and chemokines of TCR and BCR pathways in inflammatory and autoimmune disease." (PMID 32576231, 2020).
B-cell lymphomas (7 papers, 2018 to 2025). "Additionally, a screen for c-JUN and phosphorylated c-JUN of 344 CD30-positive T- or B-cell lymphomas, including 11 CD30-positive DLBCL cases, detected a striking link between CD30 and c-JUN expression." (PMID 29597249, 2018). "Indeed, the findings of our Co-IP studies hint at an interaction between BATF3 and JUN, which might be an explanation for the missing BLIMP1 expression in our B-cell lymphomas." (PMID 29662618, 2018).
diabetic nephropathy (7 papers, 2012 to 2024). "We first identified the expression level of CCL2, FOS, JUN in IgAN, lupus nephritis, diabetic nephropathy, focal segmental glomerulosclerosis, minimal change disease, and membranous glomerulonephropathy, respectively." (PMID 35464092, 2022). "Although the PI3K/Akt is a key signaling pathway for QDTS in the treatment of DN through network pharmacology and experimental verification, it needs further experiment to confirm that QDTS reduces podocyte damage in diabetic nephropathy by targeting AKT1 and JUN, such as gene intervention." (PMID 38223704, 2024).
esophageal cancer (7 papers, 2009 to 2025). A primary or metastatic malignant neoplasm involving the esophagus. "In our study, microarray data showed that three genes (FOS, JUN, BIRC5) associated with the anti-apoptotic response were elevated in the cisplatin-treated esophageal cancer cells." (PMID 24959694, 2014). "The JNK signaling pathway activator, anisomycin, has been observed to enhance JUN transcription in NIH 3T3 cells, whereas the JNK signaling pathway inhibitor, sp600125, suppressed JUN expression in esophageal cancer cells." (PMID 39457475, 2024).
heart failure (7 papers, 2013 to 2025). Inability of the heart to pump blood at an adequate rate to meet tissue metabolic requirements. "Similar to SysHF HLHS fibroblasts, RVF fibroblasts displayed enriched levels of POSTN, FAP, FOS, and JUN, consistent with a preserved activated fibroblast population observed across human heart failure etiologies." (PMID 40502733, 2025).
metastatic tumors (7 papers, 2016 to 2025). "Among them, HOXD10 and PGR are specific to primary tumor, while STAT3, JUN and JUNB are associated to metastatic tumor based on our integrative regulatory network and survival analysis." (PMID 28005952, 2016). "Our own interrogation of TCGA found JUN DNA amplification in patients with recurrent and metastatic disease was higher than patients with non-metastatic, non-recurrent primary tumors." (PMID 38023989, 2023).